CCL7 (C-C motif chemokine ligand 7)
Diseases named in the same sentence as CCL7 in open-access papers (continued):
Sharing a sentence is not in itself a finding about the gene and the disease.
allergic asthma (2 papers, 2020 to 2023). A asthma with a basis in a pathological type I hypersensitivity reaction. "In allergic asthma airway epithelial cells are one of the main producers of proinflammatory cytokines and chemokines like IL-13, IL-33, TSLP, CCL5 (Rantes), CCL7 (MCP-3), CCL17 (TARC), CCL22, and several eotaxins." (PMID 32411147, 2020).
Anxiety (2 papers, 2017 to 2024). Intense feelings of nervousness, tension, or panic often arise in response to interpersonal stresses. "These include CXCL1 (Gro-α), CCL2, CCL7 (MCP-1, MCP-3), and CCL5 (RANTES), which have also been implicated in various behavioral impairments including anxiety, depression, and LM." (PMID 29358844, 2017).
aortic aneurysm (2 papers, 2009 to 2022). A ruptured aneurysm located in the wall of the proximal portion of the descending aorta proceeding from the arch of the aorta. "It is indicated that CCL7 may be also involved in the development of aortic aneurysm via the CCR1-related mechanisms." (PMID 36109744, 2022).
atopic dermatitis (2 papers, 2016 to 2023). "In this respect, strong expression of CCL2 has been reported in the basal keratinocytes of atopic dermatitis patients, and expression of CCL7, which can attract basophils, eosinophils, mast cells and Th2 cells, can be induced by allergens in atopic skin." (PMID 27431613, 2016).
autoimmune disease (2 papers, 2023 to 2024). A disorder resulting from loss of function or tissue destruction of an organ or multiple organs, arising from humoral or cellular immune responses of the individual to their own tissue constituents. "The present study found that several genes encoding histocompatibility antigens were highly expressed in Leydig cells and T cells, and several genes associated with autoimmune disease were also abnormally expressed in testis of db/db mice, such as Ctla2a, Ccl7, and Spp1." (PMID 38817616, 2024).
Brain atrophy (2 papers, 2024). Partial or complete wasting (loss) of brain tissue that was once present. "MIP1A/CCL3 and eotaxin/CCL11 are linked to AD, MCP1/CCL2 levels correlate with neuroinflammation, brain atrophy, and cognitive decline in AD, and MCP3/CCL7 is part of a diagnostic panel for AD." (PMID 39574895, 2024).
cryptococcal infection (2 papers, 2014 to 2025). "CCL7 is known to promote a robust protective response against Cryptococcus neoformans infection in mice." (PMID 41223031, 2025).
cutaneous leishmaniasis (2 papers, 2021). Leishmaniasis affecting the skin. "and cutaneous leishmaniasis involves the production of multiple Th1-associated chemokines including CCL2, CCL7, CXCL9, and CXCL10." (PMID 34543348, 2021).
Ebola (2 papers, 2016 to 2019). "We also found several cytokines, such as CCL7 and CXCL11 (I-TAC), that showed significant changes in expression but whose protein levels have not been previously observed during Ebola pathogenesis." (PMID 27595844, 2016).
End-stage renal disease (2 papers, 2022 to 2023). "While CCL7 may be known as a proinflammatory chemokine related to kidney fibrosis progression in other chronic kidney diseases, its direct mechanistic role remains unclear in DKD." (PMID 36109744, 2022). "End-stage renal disease patients exhibit Mycobacterium-tuberculosis-specific CCL7 expression in the absence of interferon-γ." (PMID 36109744, 2022).
gout (2 papers, 2022 to 2023). A condition characterized by painful swelling of the joints, which is caused by deposition of urate crystals. "The results of RT-qPCR showed that the expressions of CCL7, CSF2RB and IL-1β were significantly up-regulated in the gout group compared with the control group (p < 0.05)." (PMID 36313318, 2022).
inflammatory bowel disease (2 papers, 2024 to 2025). A spectrum of small and large bowel inflammatory diseases of unknown etiology. "Another approach involves targeting upstream regulators of CCL2: F-box and WD repeat domain-containing protein 7 (FBXW7), an E3 ubiquitin ligase in the gut, promotes Ccl2 and Ccl7 expression, exacerbating inflammatory bowel diseases (IBDs)." (PMID 40867747, 2025).
ischemia (2 papers, 2022 to 2023). A hypoperfusion of the BLOOD through an organ or tissue caused by a PATHOLOGIC CONSTRICTION or obstruction of its BLOOD VESSELS, or an absence of BLOOD CIRCULATION. "Ccl8 and Ccl7 are kinds of chemokines that attract monocytes to the site of trauma, infection, toxin exposure, and ischemia." (PMID 36139770, 2022).
leukocytosis (2 papers, 2016 to 2023). "In the blood, we observed leukocytosis and increased amounts of the chemokines CCL2 and CCL7, as well as of GCSF; in addition, serum IgEs were elevated in Δ/Δep2 mice." (PMID 27431613, 2016).
Miscarriage (2 papers, 2014 to 2023). A pregnancy that ends at a stage in which the fetus is incapable of surviving on its own, defined as the spontaneous loss of a fetus before the 22th week of pregnancy. "In conclusion, we have found plasma concentrations of the cytokines IL-1β, IL-6 and IL-10, and the chemokines, CXCL8, CCL2, CCL5, CCL7, CX3CL1 cannot predict subsequent miscarriage." (PMID 24699265, 2014).
myocardial ischemia (2 papers, 2021 to 2022). A disorder of cardiac function caused by insufficient blood flow to the muscle tissue of the heart. "As one of the resident immune cells in the heart, during myocardial ischemia, B cells can release a variety of cytokines (including CCL2, CCL7, etc.)that chemoattract monocytes and neutrophils, thereby greatly increasing peripheral blood leukocytes myocardial infiltration." (PMID 36684609, 2022).
nephritis (2 papers, 2013 to 2019). Inflammation of renal tissue. "B1R blockade has also been reported to reduce renal inflammation by downregulating renal CCL2, CCL5, and CCL7 in the anti-GBM nephritis model." (PMID 30621761, 2019).
neuropathic pain (2 papers, 2021 to 2022). Chronic pain caused by damage to nerve fibers. "In light of our research, we propose that CCL2/7/8/CCR1 and CCL7/8/CCR3 signaling are important elements in the modulation of neuropathic pain." (PMID 36611891, 2022). "Interestingly, our results show substantial increases in the levels of the CCL7 and CCL11 mRNAs in the spinal cord and/or DRG in the early and late stages of neuropathic pain." (PMID 34795678, 2021).
osteoarthritis (2 papers, 2013 to 2023). A noninflammatory degenerative joint disease occurring chiefly in older persons, characterized by degeneration of the articular cartilage, hypertrophy of bone at the margins and changes in the synovial membrane. "Recently, it has been shown that CCL7 levels are higher in serum and synovial fluid of RA patients compared to patients with osteoarthritis." (PMID 37868981, 2023).
osteoporosis (2 papers, 2023 to 2024). A condition of reduced bone mass, with decreased cortical thickness and a decrease in the number and size of the trabeculae of cancellous bone (but normal chemical composition), resulting in increased fracture incidence. "CCL7 belongs to the CC chemokine family and its role in osteoporosis is currently under study." (PMID 37853468, 2023).
pulmonary hypertension (2 papers, 2020 to 2025). Increased pressure within the pulmonary circulation due to lung or heart disorder. "Of these chemokines and chemokine receptors, Ccl2, Ccl7, Ccl20, Ccl21, Cxcl13, Cxcl4, Ccr6 and Ccr7 have already been demonstrated to be associated with pulmonary hypertension." (PMID 32176619, 2020).
Splenomegaly (2 papers, 2013 to 2017). Abnormal increased size of the spleen. "Some multiple effects could reflect causal relationship – e.g. CCL7 influences recruitment of monocytes to spleen, which could contribute to splenomegaly." (PMID 23875032, 2013). "Ltr8 controls splenomegaly (as a main effect gene and in interaction with Ltr5), parasite numbers in liver (in interaction with Ltr4) and level of CCL7 in serum." (PMID 23875032, 2013). "Ltr1 on chromosome 2 controls in interaction with Ltr4 only parasite numbers in lymph nodes, whereas the more distal Ltr2 on the same chromosome influences development of skin lesions, splenomegaly (in interaction with Ltr3), hepatomegaly, parasite load in liver and level of CCL7 in serum." (PMID 23875032, 2013).
ulcerative colitis (2 papers, 2009 to 2024). An inflammatory bowel disease involving the mucosal surface of the large intestine and rectum. "For instance, the up-regulated expression of chemokines, such as CCL2, CCL3, CCL4, CCL7, CCL8 and CXCL8 has been shown in mucosal biopsies from patients with CD and ulcerative colitis, and this up-regulation correlated with the disease activity." (PMID 19421322, 2009).
Ureteral obstruction (2 papers, 2020 to 2022). Obstruction of the flow of urine through the ureter. "A previous study has suggested the dual role of CCL7 in the development of kidney tubular interstitial fibrosis, deleterious in early stages but beneficial in later stages in a model of unilateral ureteral obstruction." (PMID 36109744, 2022).
acute myeloid leukemia (1 paper, 2020). Acute myeloid leukemia (AML) is a group of neoplasms arising from precursor cells committed to the myeloid cell-line differentiation. "On the other hand, a study on chondrocytes showed that overexpression of HIF-2α increased CCL7/MCP-3 expression, similar to acute myeloid leukemia cells that showed a hypoxia-induced increase release of CCL7/MCP-3." (PMID 32781743, 2020).
allergic rhinitis (1 paper, 2017). Inflammation of the nasal mucous membranes caused by an IgE-mediated response to external allergens. "In conclusion, decreased eosinophil infiltration by IL-17A deficiency in allergic rhinitis is attributed at least in part to a decreased chemotactic response of eosinophils via the CCL7/CCR3 pathway." (PMID 28046055, 2017). "Allergic rhinitis is associated with elevated expression of CCL7, which may be closely associated with the recruitment of inflammatory cells." (PMID 28046055, 2017). "The suppression of nasal inflammation due of IL-17A deficiency in allergic rhinitis is partly responsible for the regulation of CCL7 secretion and eosinophil infiltration, which may be regulated via the CCL7/CCR3 pathway." (PMID 28046055, 2017). "In this study, we assessed the contribution of IL-17A to eosinophil-related inflammation via the CCL7/CCR3 pathway in experimental allergic rhinitis." (PMID 28046055, 2017). "This study was undertaken to determine whether eosinophil migration to the nasal mucosa in response to IL-17A is regulated by the CCL7/CCR3 pathway in a mouse model of allergic rhinitis." (PMID 28046055, 2017). "Consequently these results suggest that IL-17A regulates eosinophil inflammation via the CCL7/CCR3 pathway in a mouse model of allergic rhinitis." (PMID 28046055, 2017). "Thus, in this study, we investigated the regulation of eosinophil inflammation by IL-17A and the involvement of the CCL7/CCR3 pathway in a mouse model of allergic rhinitis." (PMID 28046055, 2017). "However, the exact relationship among CCL7, eosinophils, and IL-17A in allergic rhinitis in the upper airway remains unclear." (PMID 28046055, 2017). "This is consistent with previous reports of greater than 90% upregulation of CCL7 and CCR3 gene expression in the nasal mucosa of patients with allergic rhinitis." (PMID 28046055, 2017). "In the present study, CCL7 and CCR3 mRNA levels were significantly increased in the nasal mucosa in an allergic rhinitis." (PMID 28046055, 2017).
alopecia areata (1 paper, 2021). Loss of scalp and body hair involving microscopically inflammatory patchy areas. "A positive correlation was found between the serum concentration of CCL7 and the severity of alopecia areata (r = 0.281, p = 0.03), while GDF15 correlated with age at the disease onset (r = 0.509, p < 0.0001)." (PMID 34830700, 2021). "The lack of a significant difference in the serum levels of CCL7 between patients with alopecia areata and healthy controls may be associated with the low number of patients included into the analysis." (PMID 34830700, 2021).
autism (1 paper, 2025). Persistent deficits in social interaction and communication and interaction as well as a markedly restricted repertoire of activity and interest as well as repetitive patterns of behavior. "The expression of one with no established function in the brain Sult6b1, one with association to Autism Sema5a, and one with well-established role in the brain Ccl7 was examined." (PMID 38721690, 2025).
autoimmune glomerulonephritis (1 paper, 2024). An autoimmune form of glomerulonephritis (disease). "Promotion of autoimmune glomerulonephritis by IL-17 is mediated, in part, by m6A modification of RNA and functional IGF2BP2 (IMP2) binding of selected transcripts: Cebpd, Ccl7, Mt2, Il-6, and Cxcl1." (PMID 39338937, 2024).
bacterial meningitis (1 paper, 2019). Inflammation of the membranes surrounding the brain and spinal cord due to a bacterial infection. "In bacterial meningitis, the majority (23/36) of examined cytokines displayed elevated values with CCL7, TNF-α, CXCL1, and IFNγ showing consistent results with the literature (; Pinto)." (PMID 31727097, 2019). "In bacterial meningitis, multiple cytokines including CXCL10 (IP10), CCL2, CCL7 (MCP-3), CCL4 (MIP-1β), CCL5, CXCL12, IL6, IL8, and IL17 have been shown to be increased in the acute phase of the disease (; Pinto)." (PMID 31727097, 2019).
brain inflammation (1 paper, 2013). "Several immune cell chemoattractants (Ccl4, Ccl7, Cxcl9) are featured in this network, suggesting recruitment of monocytes, NK cells and T-cells to the site of brain inflammation." (PMID 23853600, 2013).
brain injury (1 paper, 2023). Acute and chronic (see also brain INJURIES, CHRONIC) injuries to the brain, including the cerebral hemispheres, CEREBELLUM, and brain STEM. "CCL7, released by astrocytes in traumatic brain injury (TBI) models and a possible marker for early BBB dysfunction, was the only investigated cytokine upregulated in both children and adult CALD patients in our study." (PMID 37683329, 2023).
breast tumors (1 paper, 2019). "We found that IL6, IL8, and CCL7 are expressed at significant levels in the normal breast, ER+ breast tumors, and the matching tumor-adjacent breast tissue." (PMID 31419632, 2019).
carcinoma in situ (1 paper, 2025). "Also, compared with carcinoma in situ, the expression of CCL7 in portal vein cancer embolus tissue was further increased." (PMID 40062588, 2025).
cardiac hypertrophy (1 paper, 2023). "While Ccl7 plays a critical role in CCR2-dependent monocyte recruitment to the heart, MFGE8 is involved in cardiac hypertrophy, cardiac fibrosis, and removal of dead cells." (PMID 37563727, 2023).
colorectal adenoma (1 paper, 2021). An adenoma that arises from the colon or rectum. "Of the examined variables, CCL7 expression in colorectal adenomas was affected solely by the growth pattern, which explained 8% of the variability in gene expression." (PMID 34884259, 2021). "Therefore, to verify the effect of the polyp sublocation on chemokine expression and discern the independent predictors of CCL2, CCL7, and CCL8 expression in colorectal adenomas, a multivariate analysis was conducted." (PMID 34884259, 2021).
Colorectal polyps (1 paper, 2021). "Therefore, this study was conducted to assess the suitability of MCP chemokines as targets for chemoprevention by determining the expression patterns of MCP-1/CCL2, MCP-2/CCL8, and MCP-3/CCL7 in colorectal polyps and the chemokine association with polyp potential for malignancy." (PMID 34884259, 2021). "This study was designed to determine the expression patterns of MCP-1/CCL2, MCP-2/CCL8, and MCP-3/CCL7 at the protein (immunohistochemistry; n = 62) and transcriptional levels (RTqPCR; n = 173) in colorectal polyps with reference to the polyp malignancy potential." (PMID 34884259, 2021). "Colorectal polyps are characterized by a significantly higher content of MCP-1, MCP-2, and MCP-3 proteins but a lower number of the respective CCL2, CCL7, and CCL8 transcripts, the downregulation of which is more pronounced in polyps with greater potential for malignancy." (PMID 34884259, 2021).
diabetic neuropathy (1 paper, 2024). A chronic, pathological complication associated with diabetes mellitus, where nerve damages are incurred due to diabetic microvascular injury involving small blood vessels that supply these nerves, resulting in peripheral and/or autonomic nerve dysfunction. "However, limited data suggest that further research is needed to fully understand whether and how CCL7 participates in the development of diabetic neuropathy." (PMID 39457105, 2024). "Additionally, it has been shown that CCR5, CCL2, CCL3, CCL5, CCL7, CCL8, and CCL12 spinal mRNA and/or protein levels are elevated in rodent models of diabetic neuropathy, with some displaying sex-related diversity." (PMID 39457105, 2024).
ductal breast carcinoma (1 paper, 2019). "Our analysis also shows higher CCL7 in ductal breast carcinoma compared to normal tissues and other histological tissue types." (PMID 30850664, 2019).
esophagitis (1 paper, 2025). An acute or chronic inflammatory disease affecting the esophageal wall. "Reduced severity of esophagitis was associated with downregulation of EGF, IL-16, CCL3, CCL7, and prolactin, suggesting decreased inflammation." (PMID 39808500, 2025).
fungal infection (1 paper, 2018). "A similar enhancement in IL-4 was seen in a lung model of fungal infection when CCL7 was neutralized." (PMID 30671055, 2018).
hyperlipidemia (1 paper, 2019). "In accordance, both CCL7 and its receptor CCR2, as well as CXCL1 have been implicated in monocyte mobilization from the bone marrow in steady state and under conditions of hyperlipidemia, respectively." (PMID 31641089, 2019).
infarction (1 paper, 2021). A localised pathological necrosis of tissue resulting from obstruction of the blood supply usually by a thrombus, an embolus, or vascular torsion. "The expression level of M2 macrophages markers (Mrc-1, YM-1, CD206, and CCL7) in the infarction and border zones on the 7th day after MI were detected to explore the ability of cardiac repair." (PMID 34214050, 2021).
interstitial nephritis (1 paper, 2020). Inflammation of the renal tubules and supporting tissues of the kidney. "Roles for Ccl7 in interstitial nephritis have been investigated in a mouse model of obstructive nephropathy." (PMID 33149203, 2020).
invasive candidiasis (1 paper, 2012). "In separate experiments, induction of Ccr1 and its ligands Ccl3, Ccl5, Ccl6, Ccl7, Ccl8 and Ccl9 by invasive candidiasis was examined in greater detail in mice injected with 1.25×105 CFU of C. albicans, which causes ∼80% mortality by day 14 post-infection." (PMID 22916017, 2012).
kidney injury (1 paper, 2021). Trauma to the kidney. "The interaction between NEAT1, PVT1, miR-429, miR-139-5p, and miR-23b-3p may regulate CaOx-induced kidney injury via CCL7 and ROBO2." (PMID 34938320, 2021).
laryngeal squamous cell carcinoma (1 paper, 2018). A squamous cell carcinoma that arises from the larynx. "In a co-culture system of CAFs and laryngeal squamous cell carcinoma, CCL7 protein levels were elevated, accompanied by rapid tumor cell proliferation, but the influence of CCL7 was negligible compared with that of CXCL12 in this study." (PMID 29915688, 2018).
macrophage activation syndrome (1 paper, 2021). A complication of rheumatic disease that is caused by excessive activation and uncontrolled proliferation of T lymphocytes and well-differentiated macrophages. "The cytokine profile in these studies is comparable to that reported in cytokine release syndromes, such as macrophage activation syndrome, which is characterized by increased expression of cytokines (IL6, IL7, and TNF) and inflammatory chemokines (CCL2, CCL7, CXC-10, and CXCL-11)." (PMID 35145507, 2021).